RNU6-1176P (RNA, U6 small nuclear 1176, pseudogene)
Gene: Small nuclear RNA gene on chromosome 1 (65,022,968 to 65,023,074, reverse strand). Ensembl gene ENSG00000212257.
Homologues: Orthologues: chimpanzee U6 (97% identical), macaque U6 (83% identical). Paralogues in human: RNU6-517P (71% identical), RNU6-338P (70% identical), RNU6-1011P (68% identical), RNU6-1024P (68% identical), RNU6-1124P (68% identical), RNU6-1187P (68% identical), RNU6-403P (68% identical), RNU6-641P (68% identical), RNU6-738P (68% identical), RNU6-1060P (67% identical), RNU6-19P (67% identical), RNU6-259P (67% identical), and 1286 more.